COL6A3 (collagen type VI alpha 3 chain)
Diseases named in the same sentence as COL6A3 in open-access papers (continued):
Sharing a sentence is not in itself a finding about the gene and the disease.
lung carcinoma (4 papers, 2015 to 2025). "We aimed to analyze the genetic association of COL6A3 and lung cancer risk among a Chinese population of Shaanxi Han." (PMID 31286980, 2019). "In the present case-control study, we investigated the connections of eight variants of COL6A3 and lung cancer risk in a Han population of China." (PMID 31286980, 2019). "Genetic models and haplotype analyses were used to calculate the association between COL6A3 SNPs and lung cancer risk." (PMID 31286980, 2019). "The aim of this study was to evaluate the association between single nucleotide polymorphisms (SNPs) in COL6A3 and lung cancer susceptibility." (PMID 31286980, 2019). "We also observed the correlation between lung cancer susceptibility and COL6A3 variants with stratification analysis by the age of 61 years." (PMID 31286980, 2019). "However, the overall information about the association between COL6A3 polymorphisms and lung cancer risk was few." (PMID 31286980, 2019). "Our findings indicated potential associations between COL6A3 polymorphisms and lung cancer risk, which may contribute to the identification of lung cancer patients in a Chinese population." (PMID 31286980, 2019). "Our findings showed potential associations between COL6A3 polymorphisms and lung cancer risk, which may contribute to the identification of lung cancer patients in a Chinese populations." (PMID 31286980, 2019). "Collectively, AHNAK, COL11A1, and COL6A3 may be potential candidates for therapeutic and diagnostic biomarkers in head and neck cancer and lung carcinoma." (PMID 26352260, 2015). "In addition, our research firstly discussed that COL6A3 gene was associated with lung cancer risk." (PMID 31286980, 2019). "Lung cancer patients with higher COL6A3 expression had a lower survival rates shown in the database of Kaplan-Meier Plotter." (PMID 31286980, 2019). "In the article, our results demonstrated that COL6A3 gene was involved in the progress of lung cancer." (PMID 31286980, 2019). "In TCGA lung cancer cohorts, Col6a3 mRNA levels are correlated with each of these ITGs." (PMID 40166934, 2025). "Furthermore, COL6A3 (q = 3.1 × 10−4, COAD) and COL5A2 (q = 1.5 × 10−4, LUAD) mutations are significantly associated with a high mutation density in colorectal and lung cancer, respectively." (PMID 26352260, 2015). "In addition, we also evaluated the association between COL6A3 SNPs and lung cancer patients with or without lymph node metastasis as well as the clinical staging of lung cancer patients." (PMID 31286980, 2019).
prostate carcinoma (4 papers, 2014 to 2020). A carcinoma that arises from epithelial cells of the prostate gland. "Many recent studies have demonstrated the important role of COL6A3 in the diagnosis and prognosis of colorectal, lung, and prostate cancer." (PMID 32934754, 2020). "COL6A3 is a secreted protein and have received growing attention due to its abnormal expression in colon, pancreatic, bladder and prostate cancer." (PMID 31249732, 2019). "Exon array analysis revealed the expression of COL6A3 alternative long isoform in colon, bladder, pancreatic, and prostate cancers." (PMID 28105922, 2016). "Previous genome exon array studies have identified cancer-specific alternative splicing of exons 3, 4 and 6 of COL6A3 in colon, pancreatic, bladder and prostate cancer." (PMID 24765172, 2014).
coronary artery disease (3 papers, 2024 to 2025). "COL6A3 levels were strongly increased by body mass index and increased coronary artery disease risk." (PMID 39856218, 2025). "The findings revealed that all 12 causal proteins, except COL6A3, exhibited significant causal associations with ischemic heart disease and MI, with the directions of effect consistent with those observed in MR results." (PMID 38689297, 2024). "These discordant MR results suggest that the circulating or tissue-specific levels of endotrophin, but not the total COL6A3 protein, modulates coronary artery disease risk." (PMID 38989470, 2024). "Therefore, we decided to focus on COL6A3 and HTRA1 as potential regulators of coronary artery disease in humans." (PMID 38989470, 2024).
diabetic nephropathy (3 papers, 2020 to 2026). "The main function of COL6A3 is to encode collagen and it is thought to be a profibrotic gene in diabetic nephropathy." (PMID 38028597, 2023). "This bioinformatics analysis identified four disulfidptosis-related genes (CXCL6, CD48, C1QB, and COL6A3) with high diagnostic value and their expression may be closely related to the declined renal function in diabetic nephropathy." (PMID 38028597, 2023). "This may be the mechanism by which COL6A3 causes kidney damage in diabetic nephropathy patients." (PMID 38028597, 2023). "In the volcano plot, CXCL6, CD48, C1QB, and COL6A3 are all highly expressed in diabetic nephropathy patients, with areas under the ROC curve of 0.908, 0.928, 0.907, and 0.895, respectively." (PMID 38028597, 2023). "This study identified four key genes (CXCL6, CD48, C1QB, and COL6A3) involved in diabetic nephropathy using a series of bioinformatics methods." (PMID 38028597, 2023). "Thus, monitoring CXCL6, CD48, C1QB, and COL6A3 expression can help in the diagnosis of diabetic nephropathy." (PMID 38028597, 2023). "The gradually decreasing glomerular filtration rate and increasing plasma creatinine with the increased expression of CXCL6, CD48, C1QB, and COL6A3 suggests that the deterioration of kidney function in diabetic nephropathy may be closely related to the expression of key genes." (PMID 38028597, 2023). "Thus, CXCL6, CD48, C1QB, and COL6A3 may be involved in kidney function deterioration in diabetic nephropathy patients." (PMID 38028597, 2023). "The expression of CXCL6, CD48, C1QB, and COL6A3 was higher in diabetic nephropathy patients than in normal controls, indicating that their expression is closely related to disease progression, so these key genes may be potential new therapeutic targets for diabetic nephropathy." (PMID 38028597, 2023). "The intersection of the two algorithms obtained four key genes for diabetic nephropathy (CXCL6, CD48, C1QB, and COL6A3) which were used to construct the nomogram." (PMID 38028597, 2023).
diabetic retinopathy (3 papers, 2023 to 2025). "COL6A3, an ECM component and M2 macrophage-related gene identified in our study, has been implicated in conditions like diabetic retinopathy." (PMID 40475059, 2025). "Immunostaining in preretinal membranes isolated from diabetic retinopathy patients showed COL6A3 accumulation in pathological tissue." (PMID 37887312, 2023). "It is important to note that further mechanistic studies are necessary to fully elucidate the precise roles of these immune cell types and their interactions with COL6A3 and IGFBP2 in the development and progression of diabetic retinopathy." (PMID 38124748, 2023).
glioblastoma (3 papers, 2021 to 2025). The most malignant astrocytic tumor (WHO grade IV). "The expression of COL6A3 is also markedly lower in normal brain tissue, pilocytic astrocytoma, astrocytomas, and oligodendrogliomas compared to glioblastoma." (PMID 41174767, 2025). "More recently, the Persano group demonstrated a role for COL6A3 in glioblastoma multiforme (GBM), where it is highly upregulated compared with normal brain and benign gliomas." (PMID 41228242, 2025). "The mechanism of tumor invasion and immune resistance involving COL6A3, COL1A1, COL1A2, LRRC15, IDO1, IL-6 and PTGS2 need to be further researched aiming to improve prognosis of aggressive glioblastoma." (PMID 33928021, 2021).
idiopathic pulmonary fibrosis (3 papers, 2014 to 2025). Idiopathic pulmonary fibrosis (IPF) is a nonneoplastic pulmonary disease that is characterized by the formation of scar tissue within the lungs in the absence of any known cause. "Among the identified candidate genes, the COL6A3, COL7A1, WNT5B, and MMP3 have been demonstrated to be associated with pulmonary fibrosis." (PMID 40034336, 2025). "In addition, the enrichment of COL6A3 was found, and it participates in ECM-receptor interaction, focal adhesion, and the PI3K-Akt signaling pathway, all of which are associated with the pathogenesis of pulmonary fibrosis." (PMID 40034336, 2025). "In keeping with this, colonic macrophages from ILC-depleted mice showed an increase in Col6a1, Col6a2, and Col6a3 transcripts that together form trimers that make up collagen type VI, previously shown to promote myofibroblast activation in the context of lung fibrosis." (PMID 32640223, 2020). "COL6A3 has been shown to be a target of the TGF-β/Smad signaling pathway, which is believed to play a role in the pathogenesis of idiopathic pulmonary fibrosis." (PMID 24647608, 2014).
keloid (3 papers, 2014 to 2022). An irregularly shaped, elevated mark on the skin caused by deposits of excessive amounts of collagen during wound healing. "Patients suffering from collagen VI related myopathies caused by mutations in COL6A1, COL6A2 and COL6A3 often also display skin abnormalities, like formation of keloids or “cigarette paper” scars, dry skin, striae rubrae and keratosis pilaris (follicular keratosis)." (PMID 25158062, 2014). "In both studies, the accumulation of collagens showed molecule‐specific (e.g., upregulated COL12A1 vs. downregulated COL6A3 in keloids)." (PMID 35435317, 2022). "These lncRNAs were associated with the related genes of keloid (ADAM12, COL6A3, and EGF)." (PMID 28101509, 2016).
lymph node metastasis (3 papers, 2019 to 2022). "The higher COL6A3 level was significantly associated with increased lymph node metastasis (P = 0.0233), whereas the elevated expression of SERPINH1 was associated with advanced age (P = 0.0034) and poor differentiation (P = 0.0231) in GC patients." (PMID 31249732, 2019). "A higher COL6A3 level was also significantly correlated with lymph node metastasis and poor prognosis in GC patients, while high levels of SERPINH1 and PLEKHG1 mRNA expression were correlated with lower overall survival (OS) in GC patients." (PMID 35892889, 2022). "Interestingly, the higher COL6A3 level was significantly correlated with lymph node metastasis and poor prognosis in GC patients." (PMID 31249732, 2019).
muscular disease (3 papers, 2019 to 2023). Myopathy is a peripheral nervous system disease consisting of any abnormal condition or disease of the muscular tissues; commonly designates a disorder involving skeletal muscle. "This suggests that the upregulated expression of COL6A3 is greater in myopathy patients harboring GNE-specific V727 mutation compared to other muscular diseases." (PMID 36980840, 2023). "Interestingly, similar to our findings, these datasets clearly showed a significant upregulation of COL6A3 as well as the majority of coexpressed genes in such muscular diseases." (PMID 36980840, 2023). "Collagen VI-related myopathies are a spectrum of muscular diseases with features of muscle weakness and atrophy, multiple contractures of joints, distal hyperextensibility, severe respiratory dysfunction and cutaneous alterations, attributable to mutations in the COL6A1, COL6A2, and COL6A3 genes." (PMID 30808312, 2019).
ovarian tumor (3 papers, 2014 to 2024). "Furthermore, highly or moderately differentiated ovarian tumours expressed lower levels of COL6A3 than poorly differentiated tumours, which indicated that the expression of COL6A3 was associated with the grade of the ovarian tumour." (PMID 31895688, 2020). "The expression of COL6A3 was significantly higher in the ovarian tumor and metastatic omentum tissues in the advanced stage than in the early stage in our EOC patients." (PMID 39125689, 2024). "Furthermore, highly or moderately differentiated ovarian tumors expressed lower levels of COL6A3 than poorly differentiated tumors, which indicated that the expression of COL6A3 was associated with the grade of the ovarian tumor." (PMID 24765172, 2014). "We further verified whether the COL6A3 protein showed staining in ovarian tumor cells." (PMID 39125689, 2024).
sarcoma (3 papers, 2019 to 2025). A usually aggressive malignant neoplasm of the soft tissue or bone. "Another study showed that COL6A3 was most predictive of overall survival in UPS patients and outperformed an established sarcoma prognostic gene panel at predicting metastasis in UPS." (PMID 40666499, 2025).
Stroke (3 papers, 2014 to 2024). Sudden impairment of blood flow to a part of the brain due to occlusion or rupture of an artery to the brain. "New genes to be considered for vascular restoration after stroke included Col6a3, Fn1, and Lamc1." (PMID 24672479, 2014). "Conversely, five genes (CLCN6, OGDHL, COL6A3 [MIM: 120250], INSR [MIM: 147670], and NOS3 [MIM: 163729]) were found in the “long survivor” group but not in the “stroke” group." (PMID 32898326, 2020).
type 2 diabetes (3 papers, 2022 to 2025). "Similarly, endotrophin is a COL6A3-derived matrikine whose plasma levels have been associated with a variety of diseases including adverse cardiovascular events, heart failure, type 2 diabetes, and cancer." (PMID 38989470, 2024). "We identified nine protein–disease associations after MR, sensitivity analyses and colocalization; these included associations of COL6A3 and PCSK9 with CAD, F11 with ischemic and cardioembolic stroke, and SPATA20 with type 2 diabetes." (PMID 39856218, 2025). "We found that fat mass independently increased plasma levels of all protein mediators (COL6A3-derived endotrophin, F11, PCSK9, C1R and SPATA20) and increased the odds of type 2 diabetes, CAD and ischemic stroke." (PMID 39856218, 2025).
amebiasis (2 papers, 2019 to 2020). A parasitic infectious disorder caused by amoebas. "Thirty-nine DEGs were present in both datasets, 13 of which, including COL6A1, COL6A2, and COL6A3, were enriched in ECM-receptor interaction, amebiasis, focal adhesion, protein digestion, and absorption pathways." (PMID 33680912, 2020). "In addition, the up-regulated DEGs were significantly enriched in 12 pathways such as NF-kappa B signaling pathway including LYN, LY96, CCL4, CD14; ECM-receptor interaction pathway including CD44, COL6A3, COL1A2, FN1 and Amoebiasis pathway including COL1A2, ITGB2, CD14, FN1." (PMID 31355054, 2019).
Cirrhosis (2 papers, 2009 to 2023). A chronic disorder of the liver in which liver tissue becomes scarred and is partially replaced by regenerative nodules and fibrotic tissue resulting in loss of liver function. "Interestingly, the collagen gene cluster expressions were significantly associated with the presence of cirrhosis (p = 0.0085, 0.04, and 0.0283 for COL6A1, COL6A2, and COL6A3, respectively)." (PMID 38041174, 2023). "It is compatible with our findings that COL6A1, COL6A2, and COL6A3 expressions, not COL1A1, were strongly associated with the presence of cirrhosis." (PMID 38041174, 2023). "Interestingly, the collagen gene cluster expressions were significantly associated with the presence of cirrhosis (p = 0.0085, 0.04, and 0.0283 for COL6A1, COL6A2, and COL6A3, respectively) but not with the survival of BA patients and age at Kasai procedure." (PMID 38041174, 2023).
craniopharyngioma (2 papers, 2019 to 2021). A benign, partly cystic, epithelial tumor of the sellar region, presumably derived from Rathke pouch epithelium. "And significantly upregulated expression of multiple genes (including COL6A2, and COL6A3) were found in adamantinomatous craniopharyngioma tumor samples." (PMID 31286980, 2019). "It is very interesting to note that the concomitant upregulation of COL8A1, COL6A2 and COL6A3 has been identified as part of the adamantinomatous craniopharyngioma signature, an aggressive rare pediatric brain tumor in which calcifications are a diagnostic hallmark." (PMID 34777248, 2021).
Down syndrome (2 papers, 2013 to 2020). "As reported in a previous study, mutations in the COL6A3 gene can lead to poor muscle development in humans and cause Down’s syndrome and muscle dystonia." (PMID 32849807, 2020).
emphysema (2 papers, 2009 to 2011). "Gene expression profiling of lung from emphysema patients identified seven candidate genes associated with emphysema severity including COL6A3, SERPINF1, ZNHIT6, NEDD4, CDKN2A, NRN1 and GSTM3." (PMID 19723343, 2009). "In conclusion, we have used microarray technology to identify seven plausible candidate genes with potential involvement in the progression from mild to moderate emphysema, two of which, COL6A3 and SERPINF1, are concordantly increased in three different studies." (PMID 19723343, 2009). "The candidate genes (CDKN2A, GSTM3, COL6A3, SERPINF1, NRN1, NEDD4 and ZNHIT6) had ontologies that were relevant to emphysema progression, including cell cycle regulation (CDKN2A), collagen (COL6A3), anti-angiogenesis (SERPINF1) and oxidative stress (GSTM3)." (PMID 19723343, 2009).
kidney tumors (2 papers, 2016 to 2024). "The alternative transcript NM_057167 of COL6A3 was also strongly up-regulated in breast, lung, prostate, and kidney tumors." (PMID 28105922, 2016).
melanoma (2 papers, 2007 to 2021). A malignant, usually aggressive tumor composed of atypical, neoplastic melanocytes. "COL6A3 encodes a fibrillar protein of the extracellular matrix believed to be involved in cell anchoring and signaling through interactions with integrins and induced by TGF-β1 in dermal fibroblasts, suggesting that COL6A3 is a good genetic marker for melanoma-associated stromal fibroblasts." (PMID 18086302, 2007). "In cell lines, expression of COL6A3 stromal cell marker was reduced to less than 1% of the value measured in matched tumors whereas periostin was expressed (at either low or high level) in about half of the melanoma cell lines." (PMID 18086302, 2007). "Hence, we compared COL6A3 expression levels in 12 melanoma cell lines and matched tumors by qRT-PCR." (PMID 18086302, 2007). "In contrast to the reduction by more than 99% of COL6A3 stromal marker mRNA in all cell lines, significant POSTN transcription was maintained in some melanoma cell lines, suggesting that both stromal cells and melanoma cells express periostin." (PMID 18086302, 2007).
neurofibroma (2 papers, 2021 to 2025). An intraneural or extraneural neoplasm arising from nerve tissues and neural sheaths. "We discovered that the three collagen VI genes (COL6A1, COL6A2, COL6A3) are abundantly expressed in neurofibroma fibroblasts." (PMID 33413690, 2021).
osteoarthritis (2 papers, 2023 to 2024). A noninflammatory degenerative joint disease occurring chiefly in older persons, characterized by degeneration of the articular cartilage, hypertrophy of bone at the margins and changes in the synovial membrane. "Together, this data suggests that the COL6A3 variant results in downstream expression changes, in part describing the osteoarthritis pathophysiology." (PMID 39021299, 2024).
osteoporosis (2 papers, 2025). A condition of reduced bone mass, with decreased cortical thickness and a decrease in the number and size of the trabeculae of cancellous bone (but normal chemical composition), resulting in increased fracture incidence. "COPD patients with osteoporosis displayed higher bronchial epithelial gene expression of COL6A3 (FDR = 0.012, nominal P-value = 6.7 × 10–7)." (PMID 40287517, 2025). "Therefore, it is tempting to speculate that the increased expression of COL6A3 in the lungs of COPD patients generates more circulating collagen VI fragments similar to what is seen in the development of osteoporosis." (PMID 40287517, 2025). "Identifying 8 key genes as potential regulatory target genes for the differentiation of mesenchymal stem cells into osteoblasts or adipocytes under the condition of disuse osteoporosis (ITGB3, LAMC1, COL6A3, ITGA8, PDGFRB, ITGA4, LAMB1, LAMA4)." (PMID 40130165, 2025). "However, further studies aimed at identifying and correlating the circulating levels of COL6A3 in COPD patients with and without osteoporosis need to be performed." (PMID 40287517, 2025).